TNF (tumor necrosis factor)
Diseases named in the same sentence as TNF in open-access papers (continued):
Sharing a sentence is not in itself a finding about the gene and the disease.
endothelial dysfunction (continued). "Cytokines such as interleukin-1, interleukin-6, interleukin-8, interleukin-17, and tumor necrosis factor-alpha are pivotal in BD pathophysiology, promoting a chronic inflammatory state leading to endothelial dysfunction and thrombotic events." (PMID 40823180, 2025). "First, they promote endothelial dysfunction by upregulating pro-inflammatory cytokines (e.g., IL-6, TNF-, and downregulating anti-inflammatory mediators, thereby triggering vascular inflammation and compromising the integrity of the endothelial barrier." (PMID 41503037, 2025). "In AAAD, inflammatory mediators such as interleukin-6 and tumor necrosis factor-α are released by macrophages and neutrophils, promoting extracellular matrix remodeling of vascular walls, endothelial dysfunction, and false lumen formation." (PMID 41285481, 2025). "Acute inhibition of PRMT1 amplified TNF‐α‐induced endothelial dysfunction and senescence via NF‐κB activation, while inhibition of NF‐κB mitigated these effects." (PMID 40135804, 2025). "Mechanistically, chronic IL-17/TNF-α–driven inflammation promotes endothelial dysfunction, arterial stiffness, and pro-thrombotic pathways—biologic plausibility that aligns with higher MI/ACS rates in observational cohorts and contemporary reviews." (PMID 41011006, 2025). "The inflamed fatty liver produces pro-inflammatory cytokines (IL-6, TNF-α) and prothrombotic factors while decreasing hepatokines fetuin-A and adiponectin which leads to increased systemic inflammation and endothelial dysfunction and atherogenesis." (PMID 41431526, 2025). "Persistent systemic inflammation (TNF-α, IL-17), endothelial dysfunction, arterial stiffness, and frequent NSAID use accelerate atherosclerosis, while metabolic syndrome and smoking amplify this risk." (PMID 41011006, 2025). "The mechanism includes increased systemic inflammation (C-reactive protein, IL-6, and TNF-α), hormone imbalance, and endothelial dysfunction." (PMID 41153819, 2025). "Pro-inflammatory cytokines (IL-6, TNF-α, IL-17) and circulating immune complexes can promote endothelial dysfunction, leading to altered choroidal perfusion, increased vascular permeability, and secondary changes in retinal and choroidal thickness." (PMID 41374071, 2025). "This inflammatory response is further enhanced by increased IL-17A, TNF-α, IL-6, and other mediators involved in developing endothelial dysfunction." (PMID 40137170, 2025). "Pro-inflammatory cytokines, such as TNF-α and IL-6, induce endothelial dysfunction by reducing nitric oxide (NO) bioavailability, impairing vasodilation, and increasing oxidative stress." (PMID 40137170, 2025). "TNF-α, primarily secreted by activated macrophages, NK cells, and T lymphocytes, induces endothelial dysfunction and microvascular thrombosis." (PMID 41471264, 2025). "Systemic inflammation increases cytokine levels (e.g., IL-6, TNF-α), promoting coagulation and endothelial dysfunction." (PMID 39857281, 2025). "Numerous cohort and meta-analysis studies support a causal or contributory role for H. pylori, particularly via mechanisms such as vascular inflammation, cytokine activation (e.g., TNF-α, IL-6), endothelial dysfunction, and dyslipidemia." (PMID 40893911, 2025). "Concurrently, hepatocyte-derived pro-inflammatory cytokines (e.g., TNF-α, IL-6) and pro-atherogenic lipoproteins are known to propagate endothelial dysfunction, thereby fostering a ‘hepato-cardio–renal axis’ of injury." (PMID 41449278, 2025). "Elevated levels of circulating pro-inflammatory cytokines, such as IL-6, TNF-α, and IL-1β, create a sustained inflammatory milieu that exacerbates vascular oxidative stress and accelerates endothelial dysfunction." (PMID 40113668, 2025). "On the one hand, weight gain can lead to increased release of adipokines (e.g., leptin, tumor necrosis factor alpha, retinol-binding protein 4) and cytokines from adipose tissue, leading to inflammatory endothelial dysfunction and metabolic dysfunction." (PMID 41357077, 2025).
endothelial dysfunction (continued). "The protective potential against endothelial dysfunction was assessed using TNF-α-induced human umbilical vein endothelial cells (HUVECs)." (PMID 41156509, 2025). "These compounds attenuate systemic inflammation by lowering circulating levels of C-reactive protein (CRP), interleukin-6 (IL-6), and tumor necrosis factor-α (TNF-α), biomarkers consistently associated with endothelial dysfunction." (PMID 41155474, 2025). "Taken together, these data suggest that PRMT1 is required for suppression of endothelial dysfunction and senescence induced by TNF‐α." (PMID 40135804, 2025). "Elevated serum uric acid can directly induce endothelial dysfunction and stimulate the production of pro-inflammatory cytokines such as TNF-α and IL-1β." (PMID 41441018, 2025). "IL- 6 promotes vascular inflammation and stiffness, while TNF-α contributes to endothelial dysfunction and arterial remodeling." (PMID 40358870, 2025). "TNF-α, another potent pro-inflammatory cytokine, contributes to endothelial dysfunction, the formation of atherosclerotic plaques, and adverse cardiac remodeling." (PMID 40724563, 2025). "This venous congestion intensifies endothelial distension, resulting in endothelial dysfunction and the activation of pro-inflammatory cytokines (e.g., IL-6, TNF-α), which exacerbate the systemic inflammatory response syndrome (SIRS) linked to CPB." (PMID 40075778, 2025). "Plaque instability, immune cell recruitment, and endothelial dysfunction are all influenced by pro-inflammatory cytokines like IL-6 and TNF-α, as well as pathways including NF-κB, TLRs, and the NLRP3 inflammasome." (PMID 40006011, 2025). "Persistent pro-inflammatory cytokines like TNF-α and IL-6 damage vascular endothelial cells, resulting in endothelial dysfunction." (PMID 40313943, 2025). "These cascades result in increased transcription of pro-inflammatory cytokines (e.g., TNF-α, IL-6, IL-1β), endothelial dysfunction, and leukocyte recruitment, which together exacerbate tissue inflammation and injury." (PMID 40926894, 2025). "The systemic inflammatory cascade is driven by cytokines such as interleukin-6 (IL-6), tumor necrosis factor-alpha (TNF-α), and interleukin-1β (IL-1β), leading to tissue injury, endothelial dysfunction, and multi-organ failure." (PMID 40959673, 2025). "The IL-6 and TNF-α reduction is particularly significant given the established roles of these cytokines in endothelial dysfunction and vascular inflammation." (PMID 40735328, 2025). "Adipose tissue releases pro-inflammatory cytokines (TNF-α, IL-6, MCP-1), causing endothelial dysfunction, vascular permeability, and tubular injury, leading to nephron loss." (PMID 40136609, 2025). "So, the comparative transcriptomics and functional assays revealed that diabetic conditions (high glucose/TNF-α) induce endothelial dysfunction via SLC3A2 suppression, triggering ferroptosis, inflammation, and fibrosis—key hallmarks of early DN." (PMID 40703306, 2025). "Elevated hs-CRP levels reflect heightened hepatic production in response to IL-6 and TNF-α, promoting endothelial dysfunction, arterial stiffness, and myocardial remodeling." (PMID 40065867, 2025). "Some authors reported that elevated levels of IL-1β, IL-6, and TNF-α not only function as immune effectors but also contribute to endothelial dysfunction, increased vascular permeability, and metabolic disturbances when produced excessively." (PMID 40806937, 2025). "CRP and IL-6 are acute-phase reactants elevated during systemic inflammation and platelet activation, whereas TNF-α is involved in promoting endothelial dysfunction, leukocyte adhesion, and vascular inflammation." (PMID 39857281, 2025). "Superantigens bypass normal antigen presentation by linking MHC class II molecules with T-cell receptors, causing massive cytokine release (IL-1, IL-2, TNF-α, IL-6, and IFN-γ), endothelial dysfunction, and multiorgan injury." (PMID 41294916, 2025).
endothelial dysfunction (continued). "Indirect mechanisms include systemic inflammation (elevated seminal IL‐6/TNF‐α), febrile insults during spermiogenesis, and endothelial dysfunction leading to erectile dysfunction (eNOS reduction, perivascular viral particles)." (PMID 41293404, 2025). "Endothelial dysfunction contributes to inflammation by increasing vascular permeability and encouraging inflammatory cells (TNF-α, IL-6) to adhere to the endothelium." (PMID 40028266, 2025). "The inflammatory response leads to the release of pro-inflammatory cytokines such as TNF-α, IL-6, and IL-1β, which contribute to endothelial dysfunction and reduced nitric oxide (NO) production, ultimately exacerbating ED development." (PMID 40529500, 2025). "To better clarify the protective effect of MP30B for TNF-α-induced endothelial dysfunction, we evaluated the gene expression of inflammatory markers related to NF-κB signaling." (PMID 39275301, 2024). "TNFα also upregulated arginase expression in endothelial cells, which contributes to oxidative stress and endothelial dysfunction in IRI." (PMID 38256155, 2024). "High levels of TNF-α and other cytokines can contribute to tissue damage, endothelial dysfunction, and severe complications like cerebral malaria." (PMID 38694310, 2024). "Endothelial dysfunction is exacerbated by proinflammatory cytokines such as TNF‐α, IL‐6, IL‐8, and IL‐18, which activate the inflammatory response, induce adhesion molecules like P‐selectin and E‐selectin, and intensify the inflammatory response." (PMID 39040847, 2024). "The inflammation induced by PM exposure is characterized by the release of pro-inflammatory cytokines, such as TNF-α and interleukins, which promote endothelial dysfunction and the formation of atherosclerotic plaques." (PMID 39857357, 2024). "This study indicates that biochanin A can target AKT1 and TNF-α to alleviate endothelial dysfunction induced by IL-6 in Perthes disease, which provides a theoretical basis for the treatment of Perthes disease by using biochanin A." (PMID 38195507, 2024). "It releases toxins, causing endothelial damage and oxidative damage in the body, and releases inflammatory cytokines, such as TNF-α, IL-6, and IFN-gamma, causing endothelial dysfunction." (PMID 38887349, 2024). "In addition, PPIs have been known to cause hypomagnesemia, which is associated with endothelial dysfunction, oxidative stress, mitochondrial dysfunction, decreased nitric oxide production, and the increased synthesis of pro-inflammatory cytokines, IL-6, and TNF-α." (PMID 39061988, 2024). "Systemic inflammation, evidenced by increased levels of pro-inflammatory cytokines such as IL-6 and TNF-α, together with biomarkers of endothelial dysfunction such as PAI-1 and CRP, demonstrate a chronic inflammatory state present in MetS." (PMID 39728125, 2024). "The aim of this study was represented by the assessment of microvascular endothelial dysfunction in RA patients by means of nailfold capillaroscopy and to assess its evolution during a period of 12 months of anti TNF-alpha treatment." (PMID 39337413, 2024). "These infiltrating lymphocytes release various pro-inflammatory cytokines (e.g., tumor necrosis factor-alpha and interferon-gamma), which promote endothelial dysfunction and vascular remodeling." (PMID 39768778, 2024). "We demonstrated that AT and ATF exert a protective effect against TNF-α-induced endothelial dysfunction." (PMID 39635433, 2024). "Endothelial dysfunction was induced by treating HUVECs with TNF-α; subsequently, the cells were treated with various concentrations of L. reuteri HY7503 to examine changes in the gene expression associated with endothelial dysfunction." (PMID 39457107, 2024). "Endothelial dysfunction in PAH is triggered by the tumor necrosis factor-α (TNF-α), which is elevated in patients with PAH and the animal models of PAH." (PMID 39113898, 2024).
endothelial dysfunction (continued). "Researchers reported that elevated urinary TNF-α level is correlated with chronic inflammation and endothelial dysfunction in obese adolescents." (PMID 39499914, 2024). "Interleukins (ILs), which are involved in inflammation, have also gained significant attention within the pathogenesis of CVDs, acting in a similar manner to that of TNF-α, thus leading to endothelial dysfunction." (PMID 38791128, 2024). "Specifically, the uncontrolled release of pro-inflammatory cytokines such as IL-1β, IL-6, and TNF-α leads to myocardial depression, endothelial dysfunction, and triggers apoptosis pathways in cardiac cells." (PMID 38326366, 2024). "Nishimatsu found that injection of the pro-inflammatory cytokine-, TNF-α-, and IL-1β-producing senescent cells in mice can impair erectile response by triggering endothelial dysfunction and nerve damage." (PMID 39022340, 2024). "Elevated androgen levels are associated with increased expression of inflammatory cytokines like TNF-α and IL-6, further exacerbating endothelial dysfunction and inflammation in PE." (PMID 39062815, 2024). "Previous studies showed that HDAC6 knockdown or TubA can protect the TNF‐induced endothelial dysfunction." (PMID 37665135, 2024). "Inflammatory cytokines, such as interleukin-6 (IL-6) and tumor necrosis factor-alpha (TNF-alpha), promote endothelial dysfunction and accelerate atherosclerotic processes in cerebral and systemic vasculature." (PMID 39735485, 2024). "Microvascular endothelial dysfunction can be assessed by nailfold capillaroscopy, with anti TNF-α medication contributing to its improvement." (PMID 39337413, 2024). "These processes lead to endothelial dysfunction and a pro-inflammatory state, characterized by increased circulating levels of inflammatory cytokines such as tumor necrosis factor-alpha (TNF-α) and interleukin-6 (IL-6)." (PMID 39596237, 2024). "Pro-inflammatory cytokines, such as IL-6 and TNF-α, are significantly elevated in lung cancer patients and contribute to endothelial dysfunction, plaque instability, and increased coagulation, all of which heighten cardiovascular risk." (PMID 39834733, 2024). "Proinflammatory cytokines, including tumor necrosis factor-alpha (TNF-α), interleukin-1 beta (IL-1β), and IL-6, are elevated in this context, contributing to vascular inflammation and endothelial dysfunction." (PMID 39497887, 2024). "They contribute to the production of pro-inflammatory cytokines such as tumor necrosis factor (TNF)-alpha and interleukin (IL)-6 and inhibit nitric oxide (NO) synthase, leading to endothelial dysfunction and vascular damage." (PMID 39057938, 2024). "Silica can increase the secretion of proinflammatory cytokines and induce endothelial dysfunction through the stimulation of tumor necrosis factor α (TNF-α) expression and/or the increased recruitment of inflammatory cells." (PMID 39062897, 2024). "Specifically, research indicates that consuming a high-fat meal increases TNF-α levels, contributing to endothelial dysfunction and oxidative stress." (PMID 38790615, 2024). "TNFα, a pro-inflammatory cytokine, contributes to pancreatic tissue injury through the induction of oxidative stress, leukocyte infiltration and endothelial dysfunction." (PMID 38927047, 2024). "Compared with static control, d-flow upregulates pro-inflammatory cytokines (e.g., TNF- tumor necrosis factor and IL-1β), cell death pathway, and the senescence pathway; all contribute to endothelial dysfunction." (PMID 38646649, 2024). "The infection induces a strong inflammatory response, including a cytokine storm (e.g., IL-6, IL-1β, TNF-α), endothelial dysfunction, and microvascular thrombosis, which exacerbate myocardial injury." (PMID 39771983, 2024). "Treatment of HUtMECs with recombinant s(P)RR or TNF-α significantly increased markers of endothelial dysfunction at both the mRNA and protein level compared with the media-only control." (PMID 38605139, 2024).
endothelial dysfunction (continued). "The aim of this study is represented by the assessment of microvascular endothelial dysfunction in RA patients by means of nailfold capillaroscopy and to assess its evolution after a period of 12 months of anti TNF-alpha treatment." (PMID 39337413, 2024). "Decreased lung function or resultant pulmonary hypertension correlates with endothelial dysfunction and increased levels of inflammatory mediators, such as C-reactive protein, interleukin-6, interleukin-8, and tumor necrosis factor-alpha." (PMID 38911586, 2024). "TNF-α can induce oxidative stress by activating NOX4 or inducing mitochondrial dysfunction, causing endothelial dysfunction, apoptosis, iNOS induction, leukocyte adhesion, and even senescence." (PMID 37894840, 2023). "Under diabetic conditions, endothelial function is impaired due to the elevation of TNF-α or IL-6, suggesting that these cytokines can also promote endothelial dysfunction in coronary arteries." (PMID 37005639, 2023). "Hydrogen sulfide ameliorates TNF-α mediated endothelial dysfunction in human endothelial cells by regulating the intrinsic apoptosis pathway." (PMID 36978982, 2023). "In diabetic patients, TNF-α induces endothelial dysfunction, which is reversed by the PPAR-γ agonist." (PMID 37745103, 2023). "TNF α inhibitors can, thus, not only reduce clinical markers of inflammation but also reduce endothelial dysfunction and oxidative stress and modify the lipid profile or prothrombic markers." (PMID 37987275, 2023). "TNF-alpha initiates the atherogenesis by increasing the level of reactive oxygen species and reducing the production nitric oxide, which results in endothelial dysfunction." (PMID 37240845, 2023). "In light of the etiological differences between cortical and lacunar strokes, i.e. large artery disease and endothelial dysfunction, respectively, this study specifically assessed the levels of plasma TNF-α in both subgroups and found similar readings." (PMID 36056287, 2023). "TNF-α is a major cytokine that induces the endothelial dysfunction by activating the expression of adhesion molecules in endothelial and vascular smooth muscle cells." (PMID 36674022, 2023). "The subsequent increased cytokine production (TNF-a and IL-6 in particular) further promotes endothelial dysfunction: IL-6 contributes to vascular permeability and TNF-a worsens glycocalyx disruption in both diseases." (PMID 36675530, 2023). "Further, TNF-α-induced endothelial dysfunction in HUVECs was significantly ameliorated by resveratrol through i) the reduction in TNF-α-induced Endothelin-1 (a vasoconstrictor) expression and ii) the increase in endothelial eNOS phosphorylation." (PMID 36829900, 2023). "TNF-α plays a role in endothelial dysfunction, vascular dysregulation, monocyte adherence to endothelial cells, vascular oxidative stress, apoptosis, and the atherogenic response, which lead to thrombosis and coagulation." (PMID 37229273, 2023). "Studies conducted on mouse models have demonstrated that elevated levels of TNF-α levels in placental tissues are linked with abnormal placenta and pregnancy loss, and that blocking TNF-α can improve endothelial dysfunction and prevent pregnancy loss." (PMID 37275894, 2023). "First, previous studies have confirmed that fibrinogen upregulates IL-1, TNF-α, and other proinflammatory cytokines expression, thereby inducing vascular inflammation and endothelial dysfunction." (PMID 37016312, 2023). "Infliximab reversed TNF-α induced endothelial dysfunction, but the effect was reversed by the presence of anti-infliximab antibodies." (PMID 37629526, 2023). "The injection of anti-TNFα antibody 3 h prior to myocardial I/R has also been shown to reduce endothelial dysfunction by reducing the production of endothelial ROS." (PMID 36902036, 2023).